TSPAN12 (tetraspanin 12)
Description:
Regulator of cell surface receptor signal transduction. Plays a central role in retinal vascularization by regulating norrin (NDP) signal transduction. Acts in concert with norrin (NDP) to promote FZD4 multimerization and subsequent activation of FZD4, leading to promote accumulation of beta-catenin (CTNNB1) and stimulate LEF/TCF-mediated transcriptional programs. Suprisingly, it only activates the norrin (NDP)-dependent activation of FZD4, while it does not activate the Wnt-dependent activation of FZD4, suggesting the existence of a Wnt-independent signaling that also promote accumulation the beta-catenin (CTNNB1) (By similarity). Acts as a regulator of membrane proteinases such as ADAM10 and MMP14/MT1-MMP. Activates ADAM10-dependent cleavage activity of amyloid precursor protein (APP). Activates MMP14/MT1-MMP-dependent cleavage activity.
Synonyms: NET2; TM4SF12; NET-2; EVR5
Tractability: Antibody: UniProt places it where antibodies can reach, with medium confidence; UniProt predicts a signal peptide or a membrane-spanning region; its Gene Ontology location is reachable by antibodies, with medium confidence. PROTAC: ubiquitination databases record sites on it.
Gene: Protein-coding gene on chromosome 7 (120,787,319 to 120,858,402, reverse strand). Ensembl gene ENSG00000106025.
Subcellular location: Cell membrane
Subcellular location (Human Protein Atlas): Microtubules; Vesicles
Gene Ontology:
Molecular function: protein binding; Wnt receptor activity
Biological process: cell surface receptor signaling pathway; regulation of angiogenesis; retina layer formation
Cellular component: membrane; plasma membrane
Genetic constraint (gnomAD): Loss-of-function variants: 16 observed, 37.12 expected, observed/expected ratio (o/e) 0.43, 90% interval 0.29 to 0.65. The upper end of that interval is the gene's LOEUF score, 0.65, which puts it in group 2 of 6, group 1 being the genes least tolerant of losing a copy. Missense variants: 306 observed, 372.49 expected, observed/expected ratio (o/e) 0.82, 90% interval 0.75 to 0.9. Synonymous variants: 117 observed, 130.9 expected, observed/expected ratio (o/e) 0.89, 90% interval 0.77 to 1.04.
Homologues: Orthologues: chimpanzee TSPAN12 (100% identical), macaque TSPAN12 (99% identical), mouse Tspan12 (98% identical), pig TSPAN12 (98% identical), rat Tspan12 (98% identical), guinea pig TSPAN12 (94% identical), rabbit TSPAN12 (91% identical), tropical clawed frog tspan12 (81% identical), zebrafish tspan12 (68% identical). Paralogues in human: CD151 (21% identical), TSPAN11 (21% identical), TSPAN6 (19% identical), TSPAN9 (19% identical), TSPAN7 (18% identical), TSPAN4 (18% identical), TSPAN8 (17% identical), CD63 (17% identical), TSPAN1 (17% identical), CD82 (17% identical), TSPAN2 (17% identical), CD37 (16% identical), and 20 more.
Diseases named in the same sentence as TSPAN12 in open-access papers:
TSPAN12 is named in the same sentence as 54 diseases in open-access papers, as found by Europe PMC text mining. Sharing a sentence is not in itself a finding about the gene and the disease. The quoted sentences say what the papers report.
Familial exudative vitreoretinopathy (25 papers, 2010 to 2025). Familial exudative vitreoretinopathy (FEVR) is a rare hereditary vitreoretinal disorder characterized by abnormal or incomplete vascularization of the peripheral retina leading to variable clinical manifestations ranging from no effects to minor anomalies, or even retinal detachment with blindness. "Mutations in human genes NDP, FZD4, LRP5 and TSPAN12 cause familial exudative vitreoretinopathy, a potentially blinding disease initially characterized by retinal hypovascularization." (PMID 28675177, 2017). "Loss-of-function mutations in Norrin, FZD4, LRP5 and Tspan12 all cause familial exudative vitreoretinopathy (FEVR) in humans." (PMID 24058663, 2013). "Mutations in Norrin, Fzd4, LRP5, β-catenin, and Tspan12 are associated with inherited diseases of the retinal vasculature, most notably familial exudative vitreoretinopathy (FEVR), and therapeutic targeting of Norrin/β-catenin signaling shows promise for modulating the BRB and BBB." (PMID 39745873, 2025). "FZD4, LRP5, or TSPAN12 mutations are also the causes of a spectrum of related congenital retinopathies such as osteoporosis-pseudoglioma syndrome, familial exudative vitreoretinopathy (FEVR), and Coats disease, each of which share resembling phenotypes with Norrie disease." (PMID 36432666, 2022). "Likewise TSPAN12 has been characterized as a disease-causing gene for exudative vitreoretinopathy (OMIM #613310)." (PMID 30745909, 2018). "In addition, mutations in the Tspan12 gene are associated with familial exudative vitreoretinopathy, a human disease caused by failure of peripheral retinal vascularization." (PMID 24206753, 2013). "In addition, array-based genomic sequence capture of a 40 Mb linkage interval combined with massively parallel sequencing was used to identify TSPAN12 as the mutated gene in patients with familial exudative vitreoretinopathy." (PMID 20808893, 2010). "In humans, mutations in NDP, FZD4, LRP5 or TSPAN12 genes are linked to familial exudative vitreoretinopathy (FEVR), which is characterized by retinal vascular defects, vision impairment, or blindness." (PMID 28675177, 2017). "Mutations in tetraspanin 12 (TSPAN12) have recently been identified as a cause of autosomal dominant familial exudative vitreoretinopathy (FEVR)." (PMID 21552475, 2011). "Disease contexts in which this mechanism is likely relevant include familial exudative vitreoretinopathy (FEVR), which is a retinal vascular disease caused by impaired norrin/FZD4 signaling, for example by mutations in the human TSPAN12 gene." (PMID 41086024, 2025). "Mutations in TSPAN12 cause familial exudative vitreoretinopathy (FEVR)." (PMID 33860000, 2021). "Mutations in candidate genes that encode for a ligand (NDP) and receptor complex (FZD4, LRP5 and TSPAN12) in the Norrin β-catenin signaling pathway are involved in the pathogenesis of familial exudative vitreoretinopathy (FEVR, MIM # 133780)." (PMID 27316669, 2016). "Norrie's disease and familial exudative vitreoretinopathy (FEVR) are retinal conditions, which present similarly to ROP engendered, engendered by a single genetic variant many of which overlap with ROP including NDP, FZD4 TSPAN12, and LRP5 from our analysis." (PMID 37492605, 2023).
hepatocellular carcinoma (6 papers, 2020 to 2025). A malignant tumor that arises from hepatocytes. "According to Wurmbach’s study, we learned that TSPAN7 and TSPAN12 are reduced in hepatocellular carcinoma." (PMID 32694936, 2020). "METTL3 mediates m6A modification of lnc-TSPAN12 to drive migration and invasion of hepatocellular carcinoma(HCC) cells, which in turn promotes hepatic metastasis." (PMID 41256854, 2025). "Additionally, TSPAN12 has been reported to be a proliferation‐promoting regulatory factor in a variety of neoplastic diseases, including small‐cell lung carcinoma, non‐small cell lung carcinoma, ovarian cancer, and hepatocellular carcinoma." (PMID 36582303, 2023). "According to a study on the expression of TSPANs in the Oncomine database about hepatocellular carcinoma, the expression of TSPAN7, TSPAN12 and TSPAN28 (CD81) proteins were lower in hepatocellular carcinoma cells than in normal liver tissue." (PMID 37752917, 2023). "Among four data sets, it was found that the expression of TSPAN7, TSPAN12, and TSPAN28 was lower in hepatocellular carcinoma patients than it was in the normal population." (PMID 32694936, 2020).
Norrie disease (6 papers, 2013 to 2025). A rare X-linked genetic vitreoretinal condition characterized by abnormal retinal development with congenital blindness. "The Norrie disease-associated mutation T119P in Norrin would also be expected to disrupt Norrin folding, but other clinically relevant Norrin mutations at positions R115 and R121 likely exert their influence by disrupting the Norrin-Tspan12 interface." (PMID 39745873, 2025). "The genes mutated in these diseases include NDP (norrin) in Norrie disease and FZD4, LRP5, and TSPAN12 in FEVR." (PMID 41086024, 2025). "Collagen, type II, alpha 1, versican (VCAN), frizzled family receptor 4, low density lipoprotein receptor-related protein 5, tetraspanin 12, and Norrie disease (pseudoglioma) genes were screened with direct sequencing." (PMID 24174867, 2013). "The cause of inadequate norrin signalling in FEVR and Norrie disease is a primary deficiency due to a genetic mutation in the norrin- > FZD4, LRP5/6, TSPAN12 signalling pathway, affecting retinal vascular development beginning in utero." (PMID 35651932, 2022).
ovarian carcinoma (5 papers, 2016 to 2024). A malignant neoplasm originating from the surface ovarian epithelium. "Tetraspanin-12 plays a critical role in cancer fibroblast cell mediant-contact inhibition and consistent with our study, TSPAN12 expression is associated with a favourable survival outcome in ovarian cancer." (PMID 38694815, 2024). "Intriguingly, we identified NDP, FZD4, and TSPAN12 to be associated with a delayed tumor progression, thus pointing to a novel tumor suppressor function of this signaling pathway in ovarian cancer." (PMID 27215396, 2016). "Tspan12 knockdown in ovarian cancer disrupts the rhythmic progression through G1-S-G2/M phases, suggesting its involvement in the intricate interplay of cyclins and CDKs, the orchestra conductors of the cell cycle." (PMID 38649381, 2024). "Tspan12 knockdown in ovarian cancer disrupts the rhythmic progression through G1-S-G2/M phases, implicating its involvement in the intricate interplay of cyclins and cyclin-dependent kinases (CDKs) like Cyclin A2, D1, E2, CDK2, and CDK4." (PMID 38649381, 2024). "TSPAN12 plays an important role in regulating cell proliferation, migration and invasion and has been recently shown to be highly expressed in some cancers, such as lung cancer, breast cancer, ovarian cancer and colorectal cancer." (PMID 33602225, 2021).
lung carcinoma (4 papers, 2020 to 2025). "Our recent study showed that QKI-5 negatively regulates miR-196b-5p, and upregulated miR-196b-5p promotes lung cancer cell migration, proliferation, and cell cycle through directly targeting the tumor suppressors, GATA6 and TSPAN12 in NSCLC19." (PMID 32963220, 2020).
breast carcinoma (3 papers, 2021 to 2024). "In contrast, TSPAN12 promotes breast cancer cell growth, but depresses tumor-endothelial interactions and metastasis to mouse lungs." (PMID 36941633, 2023). "Even more, TSPAN12 could inhibit growth of breast cancer cells, but enhance metastasis." (PMID 36941633, 2023).
colorectal cancer (3 papers, 2021 to 2024). A primary or metastatic malignant neoplasm that affects the colon or rectum. "In contrast, TSPAN12 has been found to promote the proliferation of small cell lung cancer cells and colorectal cancer cells." (PMID 36941633, 2023). "Knockdown of TSPAN12 significantly could suppress cell proliferation, migration and invasion, in vivo tumor growth, while induce cell apoptosis of both colorectal cancer and non-small cell llung cancer cells." (PMID 36941633, 2023). "TSPAN12 is highly expressed in both colorectal cancer and non-small lung cancer tissues." (PMID 36941633, 2023). "In colorectal cancer, Tspan12 was found to be upregulated compared to that in paracarcinoma tissues, and silencing Tspan12 obviously inhibited cell metastasis and growth, induced cell apoptosis of cancer cells, which could provide a novel promising therapeutic strategy against human CRC." (PMID 38389703, 2024). "High TSPAN12 expression is significantly correlated with TNM stage, tumor size and lymph node metastasis in colorectal cancer patients." (PMID 36941633, 2023).
retinal detachment (3 papers, 2021 to 2023). An eye emergency condition which may lead to blindness if left untreated. "No variations were noted in genes known to cause Wagner syndrome or other retinal detachments (ATOH7, TSPAN12, LRP5, or NDP) or in genes known to cause ocular disease." (PMID 33776059, 2021). "Patients with FEVR caused by TSPAN12 usually have abnormal retinal vasculogenesis, leading to peripheral retinal non-perfusion, ischemia, fibrovascular proliferation, and retinal detachment." (PMID 36980859, 2023).
retinal disease (2 papers, 2016 to 2023). "Pathogenic variants in genes that play key roles within this pathway, such as NDP, FZD4, TSPAN12, and LRP5, have been associated with the incidence of these retinal diseases." (PMID 37947657, 2023).
retinitis pigmentosa (2 papers, 2011 to 2019). Retinitis pigmentosa (RP) is an inherited retinal dystrophy leading to progressive loss of the photoreceptors and retinal pigment epithelium and resulting in blindness usually after several decades. "Mutations in PRPH2 (also known as TSPAN22 or RDS) and in ROM1 (also known as TSPAN23), which function together in stabilising the structure of photoreceptor outer segment discs, can cause retinitis pigmentosa, while mutations in TSPAN12 can cause familial exudative vitreo-retinopathy type 5 (EVR5)." (PMID 31073882, 2019).
age-related macular degeneration (1 paper, 2020). Age-related loss of vision in the central portion of the retina (macula), secondary to retinal degeneration. "A member of this family, TSPAN-12, was discovered as a therapeutic target for retinal vascular diseases, such as age-related macular degeneration and diabetic retinopathy." (PMID 33217969, 2020).
Autoimmunity (1 paper, 2025). The occurrence of an immune reaction against the organism's own cells or tissues. "Because immunoglobulin extravasation in Tspan12-KODBM; C1qa-KO compound mutant mice may promote autoimmunity, we examined the fundus of mice of all 4 genotypes." (PMID 41086024, 2025). "The finding that these phenotypes were not present in Tspan12-KODBM; C1qa-KO mice suggests that autoimmunity does not develop." (PMID 41086024, 2025).
colon cancer (1 paper, 2016). "We also found tumor cell selective expression of the NDP, FZD4, and TSPAN12 genes, encoding norrin, its receptor frizzled 4, and a norrin signal-amplifying component of the receptor complex, respectively, which were linked to colon cancer angiogenesis in a recent study." (PMID 27215396, 2016).
gastric cancer (1 paper, 2022). A primary or metastatic malignant neoplasm involving the stomach. "In this study, we extracted the protein from gastric cancer tissues and found that the protein expression of TGF-β1, SMAD4, and TSPAN12 was prominently decreased in gastric cancer." (PMID 35879950, 2022). "We examined TGF-β1, SMAD4, and TSPAN12 expression in gastric cancer tissues between the two groups." (PMID 35879950, 2022). "Western blot was utilized to detect TSPAN12, TGF-β1, and SMAD4 expression in gastric cancer tissues and normal tissues." (PMID 35879950, 2022).
glioma (1 paper, 2023). A benign or malignant brain and spinal cord tumor that arises from glial cells (astrocytes, oligodendrocytes, ependymal cells). "We reasonably suspect that TSPAN12 may play a positive role in gliomas." (PMID 37587203, 2023).
heart failure (1 paper, 2013). Inability of the heart to pump blood at an adequate rate to meet tissue metabolic requirements. "Our results for the first time linked directly Tspan12 downregulation with heart failure development." (PMID 24206753, 2013).
meningioma (1 paper, 2023). A generally slow growing tumor attached to the dura mater. "The most significant gene overexpressed in KLF4 meningiomas relative to AKT1 meningiomas was tetraspanin TSPAN12, which encodes a member of the transmembrane 4 superfamily." (PMID 36937440, 2023). "AKT1 meningiomas displayed high relative levels of HTRA1 and transferrin genes relative to KLF4 tumors, while KLF4 tumors overexpressed CEACAM6, DEGS2, and TSPAN12 relative to AKT1 tumors." (PMID 36937440, 2023).
metastatic tumor (1 paper, 2024). "Significant gene upregulation of these tetraspanins (CD53, ROM1, TSPAN3, TSPAN12, TSPAN15, and UPK1B) within immune cells in metastatic tumor suggests their potential involvement in the influence of immune responses." (PMID 38255741, 2024).
myopia (1 paper, 2023). "According to the clinical and genetic results, the diagnosis of the proband changed from early onset high myopia to FEVR caused by the heterozygous deletion of exon 7 in TSPAN12." (PMID 36980859, 2023). "In this case, we present a patient who was first treated as having high myopia and retinopathy but was finally diagnosed with FEVR caused by the heterozygous deletion of exon 7 in TSPAN12 with the aid of whole genome sequencing (WGS)." (PMID 36980859, 2023). "Because the proband also had high myopia, and his ERG values were highly similar to pathological myopia mean ERG values, the relationship between TSPAN12 gene mutations and ERG abnormalities requires further investigation." (PMID 36980859, 2023).
non-small cell lung carcinoma (1 paper, 2020). A group of at least three distinct histological types of lung cancer, including non-small cell squamous cell carcinoma, adenocarcinoma, and large cell carcinoma. "Our recent study demonstrated that the QKI-5 regulated miRNA, miR-196b-5p, and it functions as an onco-microRNA in non-small cell lung cancer (NSCLC) by directly targeting GATA6 and TSPAN12." (PMID 32963220, 2020).
retinoschisis (1 paper, 2023). An inherited or acquired disorder characterized by splitting of the retina into two layers. "Furthermore, the proband showed unreported TSPAN12-related phenotypes of FEVR: ERG (full-field electroretinogram) abnormalities and retinoschisis." (PMID 36980859, 2023). "In addition, since genes known to be associated with retinoschisis were ruled out by WGS in the proband, retinoschisis might have unreported phenotypes caused by the TSPAN12 mutation; however, more clinical cases are needed to confirm these." (PMID 36980859, 2023).
small cell lung carcinoma (1 paper, 2023). Small cell lung cancer (SCLC) is a highly aggressive malignant neoplasm, accounting for 10-15% of lung cancer cases, characterized byrapid growth, and early metastasis. "TSPAN12 elevation in small cell lung cancer specimens correlates with poor pathologic stage and shorter survival time." (PMID 36941633, 2023).
Stickler syndrome (1 paper, 2024). Stickler syndrome is an inherited vitreoretinopathy characterized by the association of ocular signs with more or less complete forms of Pierre-Robin sequence, bone disorders, and sensorineural deafness (10% of cases). "Exome sequencing identified 21 potential pathogenic variants of 13 genes in 20 of 75 (26.7%) probands, including genes for Stickler syndrome (COL11A1 and COL2A1; 6/20), FEVR (FZD4, LRP5, and TSPAN12; 5/20), and others (FBN1, GPR179, ZEB2, PAX6, GPR143, OPN1LW, FRMD7, and CACNA1F; 9/20)." (PMID 38243264, 2024).
viral infections (1 paper, 2023). "Variants of human TSPAN-12 have also been linked with ROP, specific types of cancer via regulation of progression, viral infections using TSPAN-12, and mental retardation." (PMID 37947657, 2023).
vitreous hemorrhage (1 paper, 2024). Blood extravasation in the vitreous humor. "Significant phenotypic difference was shown in TSPAN12 mutations with ocular developmental disorder affecting retinal exudates and neovascularization, retinal folds and detachments, vitreous hemorrhage, and macular ectopia." (PMID 38424652, 2024).